KCNK18 (potassium two pore domain channel subfamily K member 18)
Description:
K(+) channel that conducts outward and inward rectifying currents at depolarized and hyperpolarized membrane potentials, respectively. The outward rectifying currents are voltage-dependent, coupled to K(+) electrochemical gradient across the membrane, whereas the inward currents can be induced in response to activation of Ca(2+)- mobilizing receptors. Homo- and heterodimerizes to form functional channels with distinct regulatory and gating properties. In trigeminal ganglia sensory neurons, the heterodimers of KCNK18/TRESK and KCNK2/TREK-1 or KCNK10/TREK-2 inhibit neuronal firing and neurogenic inflammation by stabilizing the resting membrane potential at K(+) equilibrium potential as well as by regulating the threshold of action potentials and the spike frequency (By similarity). In thymocytes, conducts K(+) currents upon T cell receptor (TCR) signaling leading to sustained Ca(2+) influx and NF-kappa-B activation, FOXP3 transcription and positive selection of regulatory T cell (Treg) progenitor subsets. Appears to mediate the analgesics effects of hydroxy-alpha-sanshool, a metabolite naturally present in Schezuan pepper and other Xanthoxylum plants (By similarity).
Synonyms: TRESK; TRIK; K2p18.1; TRESK-2; TRESK2; MGR13
Tractability: Small molecule: an approved drug acts on it; it belongs to a druggable protein family. Antibody: UniProt places it where antibodies can reach, with high confidence; its Gene Ontology location is reachable by antibodies, with high confidence; UniProt predicts a signal peptide or a membrane-spanning region. PROTAC: a small molecule that binds it is known.
Target class: Two-pore domain potassium channel; Voltage-gated ion channel; Ion channel; Potassium channels
Gene: Protein-coding gene on chromosome 10 (117,196,957 to 117,210,752, forward strand). Ensembl gene ENSG00000186795.
Subcellular location: Cell membrane
Pathways (Reactome):
Muscle contraction: Phase 4 - resting membrane potential
Neuronal System: TWIK-related spinal cord K+ channel (TRESK)
Gene Ontology:
Molecular function: outward rectifier potassium channel activity; potassium ion leak channel activity; calcium-activated potassium channel activity; potassium channel activity
Biological process: cellular response to pH; potassium ion export across plasma membrane; potassium ion transport; regulation of CD4-positive, CD25-positive, alpha-beta regulatory T cell differentiation; potassium ion transmembrane transport
Cellular component: plasma membrane; membrane
Genetic constraint (gnomAD): Loss-of-function variants: 8 observed, 12.95 expected, observed/expected ratio (o/e) 0.62, 90% interval 0.36 to 1.11. The upper end of that interval is the gene's LOEUF score, 1.11, which puts it in group 4 of 6, group 1 being the genes least tolerant of losing a copy. Missense variants: 442 observed, 491.51 expected, observed/expected ratio (o/e) 0.9, 90% interval 0.83 to 0.97. Synonymous variants: 208 observed, 195.69 expected, observed/expected ratio (o/e) 1.06, 90% interval 0.95 to 1.19.
Homologues: Orthologues: chimpanzee KCNK18 (97% identical), macaque KCNK18 (97% identical), dog KCNK18 (73% identical), rabbit KCNK18 (69% identical), guinea pig KCNK18 (68% identical), rat Kcnk18 (68% identical), mouse Kcnk18 (66% identical), zebrafish kcnk18 (35% identical), Caenorhabditis elegans egl-23 (23% identical), Drosophila melanogaster CG43155 (22% identical), Drosophila melanogaster CG34396 (22% identical), Drosophila melanogaster sand (20% identical), and 6 more. Paralogues in human: KCNK1 (20% identical), KCNK10 (19% identical), KCNK3 (19% identical), KCNK15 (18% identical), KCNK2 (18% identical), KCNK9 (18% identical), KCNK16 (18% identical), KCNK4 (18% identical), KCNK12 (18% identical), KCNK13 (17% identical), KCNK6 (16% identical), KCNK17 (15% identical), and 2 more.
Diseases named in the same sentence as KCNK18 in open-access papers:
KCNK18 is named in the same sentence as 28 diseases in open-access papers, as found by Europe PMC text mining. Sharing a sentence is not in itself a finding about the gene and the disease. The quoted sentences say what the papers report.
migraine (55 papers, 2011 to 2025). "This would be a similar mechanism as suggested for the migraine-linked variants of the KCNK18 (TRESK) channel." (PMID 39201645, 2024). "KCNK18, a migraine susceptibility gene, encodes neuronal potassium channels that are highly enriched in the trigeminal ganglion." (PMID 39440252, 2024). "Frameshift mutations, such as F139WfsX24, in the KCNK18 gene coding for TRESK induce a complete loss-of-function in a particular family suffering with migraine with aura." (PMID 37628876, 2023). "A frame-shift mutation (F139WfsX24) in the KCNK18 gene, is associated with migraine with aura in humans." (PMID 38123150, 2023). "Another missense mutation in the KCNK18 gene (W101R) was identified in a 12-year-old male with migraine with brainstem aura and intellectual disability." (PMID 36800925, 2023). "The frameshift variant in KCNK18 which had been reported to segregate with migraine with aura, p.(Phe139Trpfs*24), was found in 196 (0.10%) controls and 10 (0.14%) cases (χ2 = 0.96, p = 0.33)." (PMID 36044383, 2022). "In humans, a dominant-negative frameshift mutation in KCNK18 segregates in patients with migraines, and a causal role for this loss of function mutation was recently established." (PMID 35586548, 2022). "Although missense and frameshift mutations with a premature stop codon in KCNK18 are linked mainly to migraine, some studies indicate that downregulation of KCNK18 contributes to neuropathic pain." (PMID 36430572, 2022). "Two frameshift mutations localized in the KCNK18 gene, c.414_415del and c.361dup, have been functionally linked to migraines." (PMID 35806193, 2022). "The same missense variants were not present in any of the ICG genes in painful- and painless-DN, with the exception of migraine-related KCNK18 variants c.414_415del and c.361dup and TRPA1 c.352C>G." (PMID 35806193, 2022). "In particular, a frameshift variant in KCNK18, p.(Phe139Trpfs*24), which had been shown to segregate with migraine with aura in a multiply affected pedigree, was found in 196 (0.10%) controls as well as in 10 (0.14%) cases (χ2 = 0.96, 1 df, p = 0.33)." (PMID 36044383, 2022). "Both KCNK18 variants have been linked to migraines and reported respectively as pathogenic, but with conflicting interpretations of pathogenicity." (PMID 35806193, 2022). "From a different subfamily is the KCNK18 gene where a frameshift mutation has been found to segregate perfectly in families with migraine with aura." (PMID 32076896, 2020). "The original finding of a KCNK18 frameshift mutation in a migraine pedigree supported by genome-wide significant linkage for the region containing KCNK18, held promise that a rare variant cause of typical migraine had been identified." (PMID 31742594, 2019). "Our data also highlight the challenges to investigating genetic associations between KCNK18 variants and migraine, as any association analysis requires robust selection of only those mutations that have deleterious effects in relevant human cells." (PMID 31742594, 2019). "A frameshift mutation (F139Wfsx24) in KCNK18 encoding for the calcium-activated K2P channel TRESK channel was associated with migraine with aura." (PMID 31031627, 2019). "A monogenic form of typical MA in a large multigenerational pedigree identified a frameshift mutation (F139Wfsx24) in the TWIK-related spinal cord potassium channel (TRESK, encoded by KCNK18), segregating with migraine." (PMID 31226929, 2019). "Overall, despite the genome-wide significant linkage in the originally reported family, the evidence for a role of gene mutations in KCNK18 in migraine genetic causation is weak." (PMID 31742594, 2019). "We have identified a novel FHM-linked M1500V mutation in SCN1A, putatively affecting the inactivation loop of the sodium channel protein and confirming previous reports found the S231P mutation in KCNK18 in a patient with migraine with aura." (PMID 26747084, 2016).
migraine (continued). "We identified a known mutation at c.691T>C, rs363315, in exon 3 of KCNK18 gene leading to amino acid substitution S231P in a female patient diagnosed with migraine with aura." (PMID 26747084, 2016). "Recently, a frameshift mutation in human KCNK18 gene encoding the TRESK channel subunits has been linked to migraine with aura in a large pedigree." (PMID 24466320, 2014). "In a recent study, we examined the presence of KCNK18 gene mutations in a large data set of Italian migraine patients (both with MA and MO) and healthy controls." (PMID 23848401, 2013). "Recently, mutations in the TRESK K2P potassium channel (KCNK18 gene) have been linked to familial migraine with aura." (PMID 23566281, 2013). "KCNK18 is one of the determinant factors of migraine-associated pain." (PMID 38249296, 2023). "However, we cannot find any report that this variant or other functional variants in KCNK18 have been observed in other migraine patients." (PMID 36044383, 2022). "Of note, these families with KCNK18 mutations exhibit migraine with aura, suggesting that reduced control over neuronal hyperexcitability due to hypofunction of TRESK channels in cortical neurons may also create susceptibility to CSD." (PMID 34858192, 2021). "Interestingly, recent studies have also reported KCNK18 variants in patients with developmental delay (DD) and intellectual disability (ID), with migraine as an associated feature in some cases." (PMID 34199759, 2021). "Variants in the KCNK18 gene have been frequently associated with migraine." (PMID 34199759, 2021). "Thus far, genetic evidence that specific frameshift mutations (such as F139WfsX24) in the KCNK18 gene, encoding the TRESK channel, cause migraine came from only one single family in which the TRESK mutation seemed to segregate perfectly with the phenotype." (PMID 32503413, 2020). "A number of KCNK18 missense variants (R10G, A34V, C110R, S231P, A233V) were also identified in unrelated sporadic migraine and control cohorts, as well as in Italian migraine patients." (PMID 32717813, 2020). "High expression levels of KCNK18 were detected in the trigeminal ganglion, which has long been implicated as the initiation point for neural, vascular and inflammatory events that underlie typical migraine symptoms." (PMID 22030984, 2011). "A frameshift mutation, F139WfsX24 in KCNK18 was originally identified in one migraine proband, as part of a larger study investigating the role of brain-expressed ion channel genes in paroxysmal neurological disorders, wherein 150 ion channel genes were sequenced in 110 unrelated migraine subjects." (PMID 31742594, 2019). "However, it is unclear whether HSV can cause migraines by causing mutations in the KCNK18 gene." (PMID 39440252, 2024). "Accordingly, K2P18.1 (TRESK) channels are supposed to play a key role in pain perception and KCNK18 was identified as a potential susceptibility gene for migraine, while a cardiac role of this channel is rather unlikely." (PMID 34831137, 2021). "Kcnk18, a TWIK-related two-pore potassium channel is involved in regulating the resting membrane potential and has been linked to migraine with aura pathogenesis." (PMID 32943709, 2020). "The role of KCNK18, the gene encoding the TRESK K2P channel, in genetic causation of migraine has been more controversial." (PMID 31742594, 2019). "The potassium channel subfamily K member 18 (KCNK18), which encodes TRESK has been suggested as a candidate gene for migraine." (PMID 31366133, 2019). "For example, the identification of KCNK18 and TRPM8 as migraine-associated genes, both highly expressed in sensory neurons, would certainly support the importance of peripheral neurons." (PMID 22027350, 2011). "One migraine proband was identified as carrying a two-bp deletion in the KCNK18 gene, which leads to premature truncation of the protein." (PMID 22027350, 2011).
migraine (continued). "Based on docking and drug likeness analysis, newly identified compounds (PB-408318540, PB-415019010, PB-414901730, PB-414901692) were proposed as potential drug molecules to target KCNK18, opening up a therapeutic option for the treatment of migraine occurrences." (PMID 38249296, 2023). "Supporting a role for two-pore-domain potassium channels in migraine, KCNK18 mutations cause non-hemiplegic familial migraine with aura." (PMID 34858192, 2021). "However, in further work, sequencing of KCNK18 in 511 sporadic migraine subjects and 505 ethnically-matched controls revealed five further missense variants and no frameshift mutations in this cohort." (PMID 31742594, 2019). "The migraine proband belonged to a large multi-generation family segregating migraine with aura in an autosomal dominant pattern, and a genome-wide linkage screen in this family showed significant linkage on chromosome 10q25.2-3, a region harbouring KCNK18." (PMID 31742594, 2019). "Authors also mention mutations of specific ion channels, such as TRESK—potassium channels encoded by gene KCNK18, which regulates the dorsal roots and trigeminal ganglia excitability; TRPM8, and others, which are linked with inherited migraine, which emphasize ion channels’ role in migraine." (PMID 40227290, 2025). "A frameshift mutation in the KCNK18 gene (F139WfsX24) was present in several members of a family suffering from familial migraine with aura, while was absent in other family relatives that did not suffer from migraine pain." (PMID 32717813, 2020). "Accordingly, we found the KCNK18 mutation in a patient with migraine without aura." (PMID 26747084, 2016). "However, not all non-synonymous KCNK18 variants linked to migraine exhibited a clear loss-of-function." (PMID 24972929, 2014). "Studies of cohorts of patients with a firm diagnosis of MwA and well characterized healthy controls are needed to further elucidate the role of KCNK18 and its product, TRESK in migraine." (PMID 36800925, 2023). "Recent studies have highlighted a potential role for new genes, like MTHFR, KCNK18, TRPV1, TRPV3, and new neurotransmission systems, like the hypocretin system, both in migraine and cluster headache." (PMID 23848401, 2013). "The authors concluded that KCNK18 should no longer be regarded as being involved in migraine etiology." (PMID 36800925, 2023). "Migraine with or without aura 13 (MGR13) has been directly linked to a specific gene, the potassium channel KCNK18." (PMID 35655042, 2022). "Since there is no other reported evidence to implicate KCNK18, we conclude that this gene and its product, TRESK, should no longer be regarded as being involved in migraine aetiology." (PMID 36044383, 2022). "KCNK18 expression in the dorsal root (DRG) and trigeminal (TG) ganglia led to a proposed role for this channel in a variety of pain pathways; moreover, an involvement in typical migraine with aura has been suggested by different authors." (PMID 34199759, 2021).
migraine headache (5 papers, 2014 to 2019). "After establishing that the KCNK18 frameshift mutation was likely to be responsible for the genetic linkage in this family, we sought to investigate whether the mutation would lead to changes in human cellular physiology relevant to migraine headache susceptibility." (PMID 31742594, 2019). "As a result, we recognized totally 7 possible causing genes (CALCA, TGFBR2, TNF, ESR1, EDNRA, KCNK18, and MTHFR) of headache in the top 10 genes." (PMID 24991551, 2014). "In addition, a migraine headache pathway of related proteins also appears in this comparison, most notably ITGB3, KCNK18, NOTCH4, and LRP1 which could be interacting with glutamate receptors." (PMID 31026304, 2019).
epilepsy (3 papers, 2021 to 2025). A brain disorder characterized by episodes of abnormally increased neuronal discharge resulting in transient episodes of sensory or motor neurological dysfunction, or psychic dysfunction. "Based on this knowledge, downregulated KCNK18 may cause epilepsy." (PMID 34588521, 2021). "It is logical to think that CCM patients with loss of function KCNK18 may develop epilepsy." (PMID 34588521, 2021). "Interestingly, downregulation of EGLN1, ELAVL4, NFE2L2 KCNK18 genes was only detected in epilepsy-related (CvsE) gene list." (PMID 34588521, 2021).
oral squamous cell carcinoma (3 papers, 2022 to 2025). "In clinical cancer, KCNK9 and KCNK18 (TRESK) were downregulated in advanced oral squamous cell carcinoma, in contrast to the findings of the animal study." (PMID 40427758, 2025).
Intellectual disability (2 papers, 2018 to 2021). "At age 10, he was diagnosed with mild intellectual disability (IQ 65), and targeted NGS revealed a heterozygous missense mutation (c.301T>C; p.Trp101Arg) in of KCNK18 gene in the proband." (PMID 30631761, 2018).
autism spectrum disorder (1 paper, 2021). A spectrum of developmental disorders that includes autism, and Asperger syndrome. "Here, we report the identification of KCNK18 biallelic missense variants (p.Tyr163Asp and p.Ser252Leu) in a family characterized by three siblings affected by mild-to-moderate ID, autism spectrum disorder (ASD) and other neurodevelopment-related features." (PMID 34199759, 2021).
Cluster headache (1 paper, 2013). A type of headache characterized by repeated attacks of unilateral pain lasting 15 to 180 minutes and associated with local autonomic signs. "Finally, KCNK18 gene involvement in tension-type headache or cluster headache has not been investigated yet." (PMID 23848401, 2013).
neurodevelopmental disorder (1 paper, 2021). A behavioral and cognitive disorder with onset during the developmental period that involves impaired or aberrant development of intellectual, motor, or social functions. "Here, we describe the identification of a family with three siblings affected by mild to moderate ID, seizures, and autistic-like behavior with different degrees of severity, carrying biallelic KCNK18 variants, supporting a possible involvement of the gene in neurodevelopmental disorders (NDD)." (PMID 34199759, 2021).
KCNK18 also shares sentences with these, for which no sentence is quoted: migraine with aura (8 papers); cancer (2); neuropathic pain (2); neuropathy (2); Paresthesia (2); Anxiety (1); autism (1); autoimmune disease (1); Autoimmunity (1); bone cancer (1); depression (1); familial hemiplegic migraine (1); hemiplegic migraine (1); immune dysfunction (1); migraine without aura (1); papillary thyroid carcinoma (1); Photophobia (1); psychiatric diseases (1); Seizure (1); urinary tract infection (1).